TOP2A (DNA topoisomerase II alpha)
Diseases named in the same sentence as TOP2A in open-access papers (continued):
Sharing a sentence is not in itself a finding about the gene and the disease.
tumor (continued). "Although further proof is clearly needed to establish a causal relationship, these data suggest that TOP2A overexpression may impair DC-mediated anti-tumor immune response in NSCLC." (PMID 31816603, 2019). "TOP2A overexpression was associated with a higher tumor grade and Ki67 index." (PMID 29587760, 2018). "TOP2A overexpression was associated with a high tumor grade (P = 0.028)." (PMID 29587760, 2018). "We also found that the expression of TS, TUBB3, and TOP2A were associated with tumor grade." (PMID 29487694, 2018). "In addition, the TOP2A level has a close relationship with the activity of these anti-tumor drugs and a high level of TOP2A is the foundation of drug susceptibility." (PMID 28106765, 2017). "Meanwhile, decreased level, altered phosphorylation or mutation of TOP2A could induce the loss of anti-tumor drug target and develop multiple drug resistance (MDR), which has been confirmed in atypical MDR studies with many cell lines." (PMID 28106765, 2017). "In addition, TOP2A overexpression in tumor tissues was also significantly associated with HBsAg in the serum (P = 0.004) and Ki-67 expression (P = 0.038)." (PMID 25695068, 2015). "Phosphorylation of TOP2A at residues within the catalytic domain affects its enzymatic activity; and mutations at some of these sites were reported to account for resistance of tumor cells to TOP2A poisons." (PMID 26560244, 2015). "Interestingly, TOP2A expression (and up regulation in this current study) has been linked to sensitivity of tumours to anthracyclines such as doxorubicin." (PMID 24023754, 2013). "Because increased expression of TOP2A in immunohistochemistry can be associated with increased response to etoposide in other tumor types, our studies suggest that expression of TOP2A could be used to guide the application of etoposide therapy." (PMID 21887332, 2011). "Additionally, the standard tools and cut-off values for estimating TOP2A status remains to be standardized, especially as TOP2A amplification may be associated with tumour size and stage." (PMID 38453781, 2024). "Moreover, TOP2A is associated with tumour grades, HBV infection, and vascular invasion." (PMID 36345011, 2022). "We speculated that the anti-tumor effects of CPX in LUAD could be associated with TOP2A regulation." (PMID 35251970, 2022). "The alterations of TOP2A may cause defective decatenation checkpoint, and then lead to the chromosome instability and additional imbalances of chromosomes in tumor cells, which results in increased cell survival, proliferation, carcinogenesis as well as the tumors’ aggressiveness." (PMID 35778520, 2022). "In our study, for all EOC patients and serous patients, the TOP2A overexpression was associated with significantly worse OS, but insignificantly better OS in endomitrioid patients, maybe due to tumor heterogeneity as well as the small and unbalanced sample sizes." (PMID 27315793, 2016). "Interestingly, ATAD2 expression was strongly restricted to the proliferating area of each tumor, as marked by Ki67 and Topoisomerase 2A (TOP2A) staining, suggesting that ATAD2 might be implicated in cell proliferation and cell cycle progression." (PMID 27612420, 2016). "While ICRF-193 suppressed tumor growth, Top2βf/f deficiency (with a compensatory TOP2α upregulation) enhanced tumor development, indicating potential roles for TOP2 isozymes in tumor formation and progression." (PMID 42192880, 2026).
tumor (continued). "Concurrently, TOP2A upregulation during tumor development correlates with therapeutic response to pharmacologic interventions in CRC." (PMID 41614789, 2025). "A distinct EPCs subpopulation with high TOP2A expression was identified, predominantly originating from tumor tissues." (PMID 40589640, 2025). "Studies have shown a statistical relationship between high expression and IHC/TOP2A copy number alteration, reduced HR expression, tumor stage, size, grade, and positive lymph nodes." (PMID 40243780, 2025). "In line with mRNA-level changes, protein levels of ABLIM1, FHL5, and MAP3K8 decreased progressively from normal tissue to tumor tissues, whereas TOP2A showed an opposite trend." (PMID 40831931, 2025). "Our analyses unveiled four hub genes—ABLIM1, FHL5, MAP3K8, and TOP2A—that consistently emerged as differentially expressed across all tumor samples when compared to normal tissue." (PMID 40831931, 2025). "Due to its crucial role, TOP2A has been identified as a primary target for developing anti-tumor chemotherapeutic drugs that inhibit its DNA-cleaving activity, such as doxorubicin, etoposide, and mitoxantrone." (PMID 40487391, 2025). "The analysis of LSIL and HSIL tissues, as well as SCC tumor samples of grades G1–3, revealed distinct expression patterns for the four proteins (TOP2A, MCM2, VCP, and p16INK4a)." (PMID 40507244, 2025). "Top2a + mal highly expressed cell cycle marker TOP2A, significantly enriched in the cell cycle, nucleus division, and DNA replication, suggesting that the tumor was in an active cell proliferation state." (PMID 39963673, 2025). "Specifically, genes such as SOX2 and TOP2A displayed hypomethylated m6A modifications, with both genes being upregulated in tumor tissues." (PMID 41209572, 2025). "High TOP2A expression was significantly associated with advanced TNM stage (p = 0.020) and deeper tumor invasion (p = 0.004)." (PMID 40765849, 2025). "TOP2A is closely related to tumor development, invasion, therapy, and prognosis through its involvement in the cell cycle and apoptosis." (PMID 40777026, 2025). "In our study, T1 exhibited the worst degree of differentiation, with the predominant cell type being tumour cells expressing signature markers such as TOP2A and HMGB2." (PMID 40099956, 2025). "Immunohistochemical analysis further supported these findings, revealing a high frequency of TOP2A positivity in tumor tissues." (PMID 40765849, 2025). "In this study, we revel that NCTD targets TOP2A to inhibit its expression, thereby inhibiting tumor progression in HCC." (PMID 40271060, 2025). "Univariate COX regression analysis demonstrated that patient age, tumor WHO grade, and TOP2A expression level were significantly associated with hazard ratio (P < 0.05)." (PMID 41284119, 2025). "Topoisomerase IIA (Top2A), which functions in releasing DNA supercoiling during replication, was also highly upregulated in tumor samples, highlighting the particular importance of DNA processing during replication in MBs." (PMID 40854122, 2025). "The TNBCvax group (a combination of all three antigens) and the individual IGF-1R, HIF-1α, and TOP2A vaccination groups showed significantly reduced tumor growth rates compared to the CpG control group." (PMID 40969744, 2025). "Four hub genes—ABLIM1, FHL5, MAP3K8, and TOP2A—were consistently dysregulated in both tumor types relative to normal tissue, suggesting their common role in tumor development." (PMID 40831931, 2025). "The cycling T cell population (cluster 11) displayed a strong signature of proliferation-associated genes including Mki67 and Top2a and included CD8+ and CD4+ cells and represented about 18% of the entire T cell population in tumours." (PMID 40473819, 2025). "Specifically, in the context of tumor cell proliferation, TOP2A is especially crucial during the S and G2/M phases of the cell cycle." (PMID 40290723, 2025).
tumor (continued). "Our data clearly indicate that TOP2A expression levels in the primary tumor are inconsistent with response, but its longitudinal expression pattern differentiates between good and poor responders." (PMID 40294066, 2025). "IFI27, KIF20A, KLK10, and TOP2A were highly expressed in tumor cells, supporting their potential as prognostic biomarkers in PAAD." (PMID 41008826, 2025). "We first assessed NEIL3 and TOP2A expression levels in an EC cell line and a non-tumor human esophageal epithelial cell line using qPCR." (PMID 39910812, 2025). "TOP2A interacts with Wnt3a to activate the Wnt signaling pathway, promoting tumor formation, progression, and metastasis." (PMID 40777026, 2025). "All hub genes, except for TOP2A, showed significant differences in expression between tumor and normal tissues." (PMID 40869426, 2025). "The results showed that Raf1_Top2α and Raf1‐Pkm2 significantly inhibited tumour growth compared with the corresponding single‐knockout group and WT group." (PMID 39073026, 2024). "We also sought to evaluate the effect of TOP2A inhibition on the markers which are involved in the CSCs, self-renewal ability and multilineage differentiation potential that are a critical for tumor cell initiation, growth, and resistance to therapy." (PMID 38957610, 2024). "PRRX1 overexpressed in MPNSTs directly interacts with topoisomerase 2 A (TOP2A) to cooperatively promote epithelial-mesenchymal transition and increase expression of tumour malignancy-related gene sets including mTORC1, KRAS and SRC signalling pathways." (PMID 38448751, 2024). "Cluster T00 highly expressed several known aggressive tumor markers (such as PTTG1, TOP2A) in comparison with other tumor epithelial clusters due to the higher proportion of cells in proliferation status." (PMID 38167466, 2024). "Targeting TOP2A is still an important strategy for OC, given its critical role in tumor cell proliferation and survival." (PMID 39727717, 2024). "The results showed that TOP2A is highly expressed in NSCLC, and its expression level is generally associated with poor prognosis and tumor stage in patients with NSCLC." (PMID 38806610, 2024). "Next, we assessed the diagnostic utility of these 7 PCD genes between KIRC tissues and adjacent non-tumor tissues, with ROC analysis showing that TOP2A had the highest AUC value." (PMID 38730293, 2024). "Consistent with previous reports, silencing TOP2A in MM inhibits tumor growth and induces DNA damage." (PMID 38593113, 2024). "The results of this study demonstrate that TOP2A plays an essential role in NSCLC tumor dissemination by stimulating the Wnt/β-catenin signaling pathway and EMT process." (PMID 38806610, 2024). "It means that when large tumor size was ≥ 3 cm and there were high total CTCs, TOP2A levels were greatly increased compared to small tumor size and low total CTCs (P = 0.021)." (PMID 38561479, 2024). "We highlight studies on the mechanisms through which TOP2A contributes to tumor progression and recurrence." (PMID 39727717, 2024). "The mean largest diameter of the primary tumour was 33 mm for the entire population and there were N = 14 (18.9%) patients with T1C tumours (N = 5 TOP2A + and N = 9 TOP2A-), and N = 57 (77.0%) patients with T2-3 tumours (N = 34 TOP2A + and N = 23 TOP2A-)." (PMID 38453781, 2024). "Elevated TOP2A expression has been observed in several solid tumors, and its overexpression is significantly correlated with an aggressive tumor phenotype, advanced disease stage, tumor recurrence, and poor survival." (PMID 39727717, 2024). "The results showed that knockdown of TOP2A reduced the tumor volume and weight of C33a cells with overexpressing HPV16 E6, down‐regulated the Ki‐67 expression, and increased the apoptosis rate of transplanted tumor cells." (PMID 38205938, 2024). "Specifically, we observed 31 genes that were highly expressed and hypomethylated, including genes associated with tumor cell proliferation and migration, such as ATP1A1, EPCAM, TOP2A, and KIF2C." (PMID 38730618, 2024).
tumor (continued). "In the GSE14994, GSE36895, GSE40435, GSE46699, GSE53757, GSE66272, and TCGA cohorts, TOP2A expression was significantly elevated in KIRC compared to adjacent non-tumor tissues." (PMID 38730293, 2024). "In contrast, TOP2A expression in high TCTCs, ER-positive, HER-2 positive expression, and tumor staging were critical risk factors." (PMID 38561479, 2024). "In untreated patients, tumor cells exhibited high levels of TOP2A expression, which was significantly reduced after platinum treatment." (PMID 39727717, 2024). "TRAP staining found that TOP2A knockdown decreased the number of TRAP+ osteoclasts at the bone-tumor interface." (PMID 37980167, 2023). "AURKA and TOP2A were downregulated in both tumor cell lines but were, conversely, strongly upregulated in HMECs." (PMID 37888205, 2023). "TOP2A is related to tumor development and poor survival outcomes by regulating cell proliferation and the CRC cell cycle." (PMID 36900162, 2023). "For example, TOP2A is a cellular topoisomerase that determines the response of tumor cells to chemotherapy, and the chemosensitivity of tumor cells can be determined by intracellular topoisomerase level." (PMID 37248280, 2023). "Previous studies have shown that TOP2A expression levels were the main determining factors of tumor cell response to TOP2A poisons." (PMID 37393350, 2023). "qRT-PCR and IHC assay demonstrated that both the mRNA and protein levels of TOP2A were elevated in LIHC-BM lesions compared with the LIHC tumor tissues." (PMID 37980167, 2023). "As the tumor progressed, the expression level of TOP2A was also increased in LUAD, LIHC, SKCM, PRAD, BRCA, and KIRC tumors." (PMID 37980167, 2023). "This is result is also consistent with the fact that about 50% of BAZ2Ahigh/KDM1Ahigh and BAZ2Ahigh/TOP2Ahigh corresponds to tumours with high TOP2A and KDM1A expression levels, respectively (Q1)." (PMID 37184661, 2023). "Meanwhile, TOP2A was negatively correlated with the Stromal score and ESTIMATE score, which also suggested that the high expression of TOP2A was positively correlated with tumor purity and poor prognosis." (PMID 37980167, 2023). "Four weeks after injecting control or TOP2A-knockdown HCCLM3 cells directly into the bone marrow cavity of mice tibia, a small animal bioluminescent imaging device detected that TOP2A depletion reduced tumor expansion in the tibia." (PMID 37980167, 2023). "It has been found that the TOP2A positivity rate in tumor tissue is an independent prognostic factor and is correlated with high expression and good prognosis." (PMID 37461124, 2023). "The DNA methylation level of the TOP2A gene promoter in tumor tissues was significantly lower than that in their adjacent normal tissues." (PMID 37980167, 2023). "Analysis of the clinicopathological information indicated that the TOP2A expression level is related to the degree of tumor differentiation, recurrence, and metastasis of HCC patients treated with sorafenib." (PMID 37781045, 2023). "It is worth noting that TOP2A was not only positively correlated with PI3K / AKT/ mTOR tumor signal pathway but also correlated with metastasis-related EMT, MMP protein, angiogenesis, and the Hippo-YAP pathway." (PMID 37980167, 2023). "More importantly, in vitro and in vivo experiments confirmed that TOP2A was responsible for bone-specific metastatic and tumor-induced osteolysis in LIHC." (PMID 37980167, 2023). "Topoisomerase II Alpha (TOP2A) is an enzyme that controls and changes the topological state of DNA, and can exert anti-tumor effects." (PMID 36755568, 2023). "Drugs targeting TOP2A activity, including etoposide and doxorubicin, induce double-strand breaks (DSBs), resulting in tumor cell death." (PMID 37888205, 2023). "The TOP2A vaccination significantly reduced tumor volume as compared to the adjuvant control (CpG only) with an average tumor size of 736 mm3 in adjuvant controls vs. 11 mm3 in vaccinated mice (p < 0.05)." (PMID 37880313, 2023).
tumor (continued). "Here, by Cox modeling, we develop IRS—which combines TMB with CD274, PDCD1, ADAM12 and TOP2A quantitative expression—to predict pembrolizumab rwPFS (648 patients; 26 tumor types; IRS-High or -Low groups)." (PMID 36750617, 2023). "The fact that a high TOP2A expression level was also related to aggressive tumor features such as grade and pT stage is consistent, however, with a prognostic role of this parameter in untreated patients." (PMID 38137396, 2023). "This is consistent with previous findings in HeLa and Jurkat cells, which suggested that inhibition of TOP2A in tumor cells can induce apoptosis through a caspase-dependent pathway." (PMID 37818158, 2023). "By scRNA-seq analysis, we found a group of DCs, which we named tumor-associated DC (TADC) because this DC subset uniquely expresses tumor-associated genes such as Pclaf, Spc24 and Top2a, highly expressed Il22ra2 in Clec7a−/− mice but not in WT mice." (PMID 36932082, 2023). "Immunohistochemistry was performed to evaluate TOP2A protein levels in tumor tissues, and patients were divided into two groups according to their expression of TOP2A." (PMID 37781045, 2023). "To further confirm these results, we collected ten pairs of HCC and adjacent normal tissues and found that EZH2 and TOP2A protein levels were higher in tumor tissues than in adjacent normal tissues." (PMID 38008711, 2023). "In the clinical group Tumor status: Tumor free and with tumor, the genes TOP2A, BIRC5, VEGFA had highly statistical significance, while the genes HIF1A, ACSL3, FTH1 didn’t have statistical significance." (PMID 37248280, 2023). "At present, doxorubicin, which can selectively inhibit TOP2A, is the most important first-line drug used for general tumor chemotherapy." (PMID 37781045, 2023). "Fortunately, a commonly used anti-tumor drug, doxorubicin, can selectively inhibit TOP2A in clinical practice." (PMID 37781045, 2023). "The results of differential expression analysis of MALAT1 and TOP2A in BC showed that the expression of MALAT1 and TOP2A in tumor tissues increased significantly in patients' tissues compared to normal tissues." (PMID 37244966, 2023). "In TOP2A vaccinated mice, tumor weight in the TOP2A vaccinated mice was also significantly reduced by nearly 85%." (PMID 37880313, 2023). "Commonly altered at both copy number and expression level in tumor cells, TOP2A is considered as a key player of decatenation checkpoint." (PMID 35778520, 2022). "The tumours of fifty-nine patients positively expressed TOP2A, 13 tumours negatively expressed TOP2A, and 37 tumours positively expressed RRM1." (PMID 35711974, 2022). "CPX significantly down-regulated TOP2A expression, and TOP2A knockdown combined with CPX exerted synergistic anti-tumor effects." (PMID 35251970, 2022). "High expression of TOP2A was related to poor prognosis and advanced pathological stages in most cases, and TOP2A genetic alterations was existed in some tumor types." (PMID 35778520, 2022). "In this study, the differential expression of TOP2A in tumor tissues and normal tissues was also analyzed online from the TIMER database." (PMID 35033076, 2022). "IHC also showed that TOP2A expression in the CPX group was significantly reduced in animal xenograft tumor samples." (PMID 35251970, 2022). "Metadherin (MTDH), glutaminyl-peptide cyclotransferase (QPCT), topoisomerase II alpha (TOP2A), programmed death ligand 1 (PD-L1), and tumor-infiltrating lymphocytes (TILs) were evaluated in BC tissues pre-neoadjuvant for potential biomarkers." (PMID 35875123, 2022). "Previous studies have respectively reported partial molecular mechanism of TOP2A in several tumor types." (PMID 35778520, 2022). "The infiltration level of CAFs presented a statistically positive relationship with TOP2A expression in various tumor types, namely CESE, ESCA, HNSC, HNSC-HPV−, KICH, KIRC, KIRP, LGG, PCPG, SKCM, SKCM-Metastasis as well as THCA." (PMID 35778520, 2022).